MCL1 (MCL1 apoptosis regulator, BCL2 family member)
Diseases named in the same sentence as MCL1 in open-access papers (continued):
Sharing a sentence is not in itself a finding about the gene and the disease.
lymphoma (continued). "In addition, Mcl-1 expression has been correlated with tumor grade and was determined to be predominant in high-grade lymphomas versus low-grade lymphomas." (PMID 38731446, 2024). "Therefore, using pre-clinical mouse and human models of aggressive lymphoma, we sought to predict factors likely to contribute to the development of resistance in patients receiving MCL-1-targeting BH3-mimetic drugs." (PMID 36755070, 2023). "Next, we explored the ability of BCL-2 and MCL-1 inhibitors to enhance PLK4 action in lymphoma." (PMID 36934096, 2023). "Members of the lymphoma apoptosis regulatory family are considered to be regulators of cell death, including Bcl-2, Bcl-xl, and MCL-1, acting as chemical inhibitors of the pro-apoptotic protein Bax, which inhibits the release of Bax and cytochrome c and exerts an anti-apoptotic effect." (PMID 36851415, 2023). "The MCL1-rs9803935 T > G, Survivin-rs17882312 G > C, BIRC5-rs17882312 C > G, and Survivin-rs9904341 G > C genotypes and alleles were found to be substantially related to the risk of lymphoma in patients compared to controls." (PMID 36831357, 2023). "Indeed, it has been shown that inhibition of the mTORC1 complex, and by extension Mcl-1 translation, shows antitumor effects in lymphoma as a single agent and in combination with venetoclax." (PMID 37684238, 2023). "One plausible explanation for our finding that loss of BAX but not loss of BAK confers resistance to MCL-1 inhibitors is that Eμ-Myc lymphoma cells depend only on BAX to undergo cell death." (PMID 36755070, 2023). "Similarly, examination of a panel of lymphoma cell lines found that BFL-1+ lymphomas were less sensitive to BH3-mimetics targeting MCL-1 and BCL-2." (PMID 35900226, 2022). "Interestingly though, our developed lymphoma cell lines also displayed sensitivity to MCL-1 inhibition." (PMID 35961968, 2022). "Moreover, IACS‐010759 synergized not only with venetoclax to kill MYC/BCL2 DHL tumor cells in vivo and in vitro, as previously shown with tigecycline, but also with the MCL1 inhibitor S63845 against BCL2‐negative lymphoma cell lines." (PMID 36214609, 2022). "Eμ-Myc lymphomas are highly reliant on the pro-survival protein MCL-1 for their sustained survival." (PMID 35961968, 2022). "So far, therapies for lymphomas and other cancers have focused on inhibition of cellular regulatory proteins (i.e., the mitoprotective members of the Bcl-2 family such as Bcl-2, Bcl-xL, and Mcl-1)." (PMID 35806271, 2022). "Mcl-1 is critical for the survival of rapidly proliferating hematopoietic progenitors and non-transformed pro-B and pre-B cells, which are thought to be the cells of origin in the Eμ-Myc driven lymphoma mouse model." (PMID 34336857, 2021). "The expression of HSP-70, c-Myc, Bcl-2, Mcl-1, xIAP, and Bcl-xL, as well as other molecules, such as phosphatidylinositol, ERK, MAPK, chemokines, cell surface receptors, and G proteins in lymphoma cell-derived EVs, has also been linked to resistance to immunotherapy." (PMID 33805807, 2021). "We then profiled Toledo and OCI-Ly8 high-grade lymphoma cell lines to determine which drugs could reduce MCL1 expression and potentiate venetoclax responses." (PMID 33670870, 2021).
lymphoma (continued). "Moreover, MCL-1 is critical also for the development of B-cells lymphoma and its down-expression in lymphomas can be compensated by altered levels of other cell death regulators, such as BIM and/or BCL-xL." (PMID 32549409, 2020). "As in the mouse model, we found that expression levels of MCL1 were profoundly downregulated by TYK2 depletion, suggesting that TYK2’s ability to promote lymphoma cell survival may be mediated through MCL1." (PMID 30131584, 2019). "In addition, OTSSP167 also sensitized the lymphoma cells to the clinically relevant Bcl-2 inhibitor venetoclax by strongly reducing Mcl1 levels." (PMID 31740676, 2019). "However, increased levels of MCL-1 mRNA are suggested to be essential for sustained growth, survival, and resistance to chemotherapeutics in multiple types of lymphoma as well as CLL." (PMID 30671383, 2018). "Thus we examined the expression level of c-Myc, and Bcl-2 family proteins such as Mcl-1, Bcl-xl and xIAP, which provide aberrant survival advantage for lymphoma cells, in OCI-LY3 EXOs and its parental cell line." (PMID 30103789, 2018). "While this interest has resulted in advances in treatment of hematogenous cancers, particularly in the inhibition of Bcl-2 and Bcl-xL in lymphoma, effective inhibitor treatments of solid tumors remains a challenge, particularly the effective targeting of Mcl-1." (PMID 28423654, 2017). "Therefore, combined targeting of BCL-2 and MCL-1 is a potential treatment strategy especially in aggressive lymphomas that are refractory to standard chemotherapy." (PMID 29269870, 2017). "However, BCL6 inhibition also activates BCL6 target genes such as BCL2 and BCL2L1 (BCL-XL), and secondary MCL1, which can sustain lymphoma survival by suppressing the activity of pro-apoptotic BH3 proteins." (PMID 26657288, 2016). "Indeed, feeding lymphoma-bearing mice with a diet having 25% less carbohydrates was sufficient to decrease Mcl-1 expression by 50% in lymphoma cells." (PMID 27689327, 2016). "Consequently, we showed that once BCL6 activity is suppressed, additional targeting of resistance mechanisms such as BCL2/BCL-XL/MCL1 provides superior anti-lymphoma effect." (PMID 26657288, 2016). "We investigated if a modulation of the diet could impact on Mcl-1 expression using a Myc-driven lymphoma model." (PMID 27689327, 2016). "Moreover, the lymphomas that arose when MCL-1 levels were diminished appeared to have been selected for reduced levels of BIM and/or increased levels of BCL-XL." (PMID 26962682, 2016). "Moreover, lymphomas that arose in Eμ-Myc;CD19-Cre;Mcl-1fl/+ and Eμ-Myc;CD19-Cre;Mcl-1fl/fl mice despite loss of one Mcl-1 allele appeared to have undergone selection for upregulation of BCL-XL and/or a reduction in pro-apoptotic BIM." (PMID 26962682, 2016). "While reducing food intake (caloric restriction) is a very efficient way to reduce Mcl-1 expression and to sensitize lymphoma cells to targeted therapies, the clinical relevance of such approach might be limited by the general condition of the patient." (PMID 27689327, 2016). "In order to determine whether the decrease in Mcl-1 protein expression represents a decrease in lymphoma B cells, lysates from sorted B cells isolated from lymphoma-bearing spleens were analyzed by Western blot." (PMID 27689327, 2016). "Among these, Bcl-2, Bcl-XL, and Mcl-1 are frequently overexpressed in lymphomas." (PMID 23431463, 2013). "Resistance to ABT-737 occurs in lymphoma cells with high expression of Mcl-1 and/or Bfl-1/A1." (PMID 23431463, 2013). "After interaction with BAFF-R and other receptors, BAFF activates NF-κB, which leads to the resistance to apoptosis of lymphoma B cells by upregulation of the antiapoptotic proteins Bcl-2, Bcl-xL, and Mcl-1 and downregulation of proapoptotic proteins such as Bax." (PMID 23272079, 2012). "In our recent studies, we have also concluded that the Bax:Mcl-1 ratio may govern the response of lymphoma cells to BH3-mimetic small molecule inhibitors such as TW-37." (PMID 19220884, 2009).
lymphoma (continued). "By 28 hrs post-drug delivery, there was a reduction in the amount of Mcl-1, Cyclin D1, and c-Myc protein levels in Pten+/−Eμ-Myc lymphomas relative to vehicle-treated controls (compare lanes 2–6 to 1) whereas the levels of β-actin or Bcl-2 did not appreciably change over this time period." (PMID 19412536, 2009). "Besides MDR1, MCL1 was extensively studied in cancer and overexpression, and amplification of MCL1, a Bcl-2 family member anti-apoptotic protein, has been linked with poor prognosis in various solid and hematological cancers including AML and lymphoma." (PMID 38916832, 2024). "However, these lymphoma cells could be killed by combined targeting of MCL-1 and BCL-XL using S63845 and the BCL-XL-specific BH3-mimetic drug A-1331852." (PMID 36755070, 2023). "Moreover, MCL-1 over-expression greatly accelerates the development of c-MYC driven lymphoma." (PMID 36342579, 2023). "Furthermore, MYC-driven lymphomas are highly dependent on MCL1 for survival." (PMID 37766215, 2023). "However, the degree of MCL-1 dependence has generally been correlated with more aggressive lymphoma subtypes and, therefore, while there is a rationale to explore MCL-1 inhibitors in indolent lymphomas, the anticipated efficacy may be lower." (PMID 35267584, 2022). "Moreover, while BCL2 transgenic mice only develop tumors with a low frequency or after cooperation with other oncogenes (e.g., MYC), MCL1 transgenic mice were shown to develop lymphomas (predominantly FL and DLBCL) with high probability (>80%), although with a long latency (over 6 months)." (PMID 34576319, 2021). "Therefore, we hypothesized that OTSSP167 might sensitize the lymphoma cells to venetoclax by reducing Mcl1 levels." (PMID 31740676, 2019). "Remarkably, the median lymphoma-free survival of Eμ-Myc;Rag-1-Cre;Mcl-1fl/+ mice (346 days) was far longer than in control Eμ-Myc (91 days) and Eμ-Myc;Rag-1-Cre mice (129 days, P**=0.003), clearly demonstrating the importance of MCL-1 in c-MYC-induced lymphomagenesis." (PMID 26962682, 2016). "Furthermore, in ALCL cell lines and in a xenografted model the increased expression of miR-29a modulated apoptosis through inhibition of MCL-1 expression, with a concomitant tumor growth reduction suggesting a potential new tool to affect tumorigenesis in these lymphomas." (PMID 25232701, 2014). "In aggressive lymphomas, alterations in the MYC oncogene and anti‐apoptotic regulators such as MCL1 and BCL2 are frequent promoters of this phenotype." (PMID 41169010, 2026). "On the other hand, MCL1 expression was significantly higher in healthy CD34 + cells compared to healthy MSC and lymphoma cell lines." (PMID 39531065, 2025). "To further validate these in vitro data, we analyzed the expression of Mcl-1 and SOD1 in a panel of patient-derived lymphoma biopsies." (PMID 40707672, 2025). "For marginal zone lymphoma cells, levels of BCL2 family members were similar to DLBCL, but they were quite sensitive to venetoclax, navitoclax, and MCL1 inhibition, and combination treatments with venetoclax showed cooperation." (PMID 38893249, 2024). "The analysis of the MCL-1 level in either the JEV, ZIKV, or DENV-infected human lymphoma cells, U937, showed the correlation between the MCL-1 downregulation and the effectiveness of virus propagation (manifested in the viral titer)." (PMID 38256213, 2024). "No marked differences in the other BCL-2 family proteins examined (BCL-XL, BCL-2, MCL-1, BIM) were observed between lymphomas of the two genotypes." (PMID 37567974, 2023). "MCL1 is a member of the BCL2 family of anti-apoptotic, prosurvival proteins and is frequently overexpressed in high-grade NHL lymphomas and MM." (PMID 37766215, 2023). "There are several clinical trials ongoing for Mcl-1 inhibitors, for example MIK665 (also named S64315) is tested in phase I trials for refractory or relapsed lymphoma or MM patients." (PMID 36986514, 2023).
lymphoma (continued). "In BCL2‐negative lymphoma cells, instead, killing by IACS‐010759 was potentiated by the Mcl‐1 inhibitor S63845." (PMID 34632715, 2022). "The elevated BCL-2 expression observed in the CRISPRa transduced lymphoma cells substituted for MCL-1 and hence increased resistance to the MCL-1 selective inhibitor S63845." (PMID 35961968, 2022). "In support of this concept, the BCL2 inhibitor venetoclax potentiated the cytotoxic activity of IACS‐010759 in MYC/BCL2 DHL cells, while the Mcl‐1 inhibitor S63845 did so in MYC‐translocated, BCL2‐negative lymphoma cell lines." (PMID 34632715, 2022). "The critical role of MCL1 during MYC-driven lymphomagenesis and for the continued survival of lymphoma cells has been repeatedly demonstrated." (PMID 34576319, 2021). "MCL1 locus (1q21) gain/amplification and constitutive activation of the STAT3 pathway were identified as key drivers of aberrant MCL-1 expression in this lymphoma subtype." (PMID 32290241, 2020). "Previous studies showed that venetoclax combined with the selective MCL1 inhibitor S63845 had a significant synergistic killing effect on MCL cell lines in vitro and induced long-term lymphoma-free survival in MCL xenograft models." (PMID 33292251, 2020). "For instance, in aggressive MCL, MCL-1 inhibition, both alone or together with venetoclax, ibrutinib, or BCL-xL inhibition synergistically induced apoptosis and effectively eradicated lymphoma cells protected by the microenvironment." (PMID 33139702, 2020). "Mice overexpressing MCL-1 in hematopoietic stem/progenitor cells are prone to malignant transformation, particularly (MYC-driven) lymphomas of the B-cell lineage." (PMID 33308268, 2020). "S63845 is a new selective MCL1-inhibitor with potential use across a number of hematological malignancies including myeloma, AML, and lymphoma." (PMID 31718075, 2019). "Stem/progenitor cell lymphomas also dominated in Eμ‐BCL2/Eμ‐MYC DT, Eμ‐Bclx/Eμ‐MYC DT and Vav‐Mcl1/Eμ‐MYC DT mice 29, 31, 32, while Vav‐BCL2/Eμ‐MYC DT mice developed IgM−CD19+CD43+ pro‐B cell tumours." (PMID 29498802, 2018). "Our data provide a mechanistic rationale for combination strategies to disrupt lymphoma cell codependency on BCL2 and MCL1 proteins in DLBCL." (PMID 30404918, 2018). "As previously, lymphoma-bearing mice were fed with a Low CHO or a Low PROT diet for 5 days and Mcl-1 mRNA levels from the lymph nodes were analyzed by real time quantitative PCR." (PMID 27689327, 2016). "High levels of Mcl-1 and Bcl-XL have been reported to be a mechanism of both de novo and acquired resistance to ABT-199 in lymphoma cell lines, which is overcome by the addition of mTOR inhibitors, and possibly with acadesine." (PMID 26110568, 2015). "We hypothesized that the combination of enitociclib, venetoclax and prednisone (VVIP) would be active in R/R aggressive lymphomas, many of which express increased MYC, BCL2 and MCL1." (PMID 41169010, 2026). "BCL-2, MCL-1, and BCL-XL are frequently over-expressed in lymphomas and leukaemias." (PMID 36342579, 2023). "To this end, we sought to identify factors that could confer resistance to MCL-1 inhibitors using murine and human models of highly aggressive, MYC-driven lymphoma." (PMID 36755070, 2023). "When cyclin-dependent kinase 9 (CDK9) inhibitors were applied to down-regulate both BFL-1 and MCL-1, an induction of apoptosis in BH3-mimetic–resistant lymphoma cells was observed, and regression of BFL-1+ DLBCL was achieved in patient-derived xenograft (PDX) models." (PMID 35900226, 2022). "Our study, in contrast to recent report in VEN-RE lymphoma, found reduced basal and maximal OCR, decreased mitochondria number with dysmorphic cristae and reduction of TCA cycle intermediates in VEN-RE AML cells overexpressing MCL-1." (PMID 35185150, 2022). "Furthermore, in BCL2‐negative, MYC‐translocated lymphoma cell lines, the cytotoxic activity of IACS was potentiated by the Mcl‐1 inhibitor S63845." (PMID 34632715, 2022).
lymphoma (continued). "RCHOP and venetoclax should be effective in high-grade lymphomas that express BCL2 protein, are not class B, and co-depend on BCL2 and MCL1 (53% of our diagnostic DLBCL samples)." (PMID 33670870, 2021). "DLBCL, the most prevalent lymphoma subtype, can be divided into BCL2 and MCL1-dependent categories." (PMID 34576319, 2021). "At the same time, Duvelisib can reduce MCL-1 mRNA and expressed protein to a small extent, because MCL-1 can promote the survival of malignant lymphoma cells, which may increase the sensitivity of CLL cells to venetoclax[134." (PMID 34976824, 2021). "Although the loss of one MCL-1 allele does not significantly impair the survival of normal B lymphocyte-like cells, it almost completely abrogates the development of MYC-driven lymphomas." (PMID 33883020, 2021). "Accordingly, various studies showed that targeting MCL-1, either through genetic- or BH3 peptide-based approaches, makes resistant cells significantly more sensitive to BCL-XL/BCL-2 inhibition, and abrogates growth of MCL-1-dependent cancers (e.g. AML and MYC-driven lymphoma)." (PMID 34515749, 2021). "Similarly, in lymphoma experiments, resistance to ABT-737 was affected through a shift in BCL-2 family member dependency by the upregulation of MCL-1 or BFL-1/A1." (PMID 32131385, 2020). "Interestingly, antilymphoma activity of hippuristonal was blocked by overexpression of the anti-apoptotic proteins BCL2 or MCL1 and hippuristonal synergized with the BCL2 inhibitor ABT-737 to induce of apoptosis of MYC lymphoma cells in vitro." (PMID 32924027, 2020). "The pro-survival BCL-2 proteins: B-cell leukemia/lymphoma-2 (BCL-2/BCL2), myeloid cell leukemia-1 (MCL-1/MCL1) and B-cell lymphoma-extra large (BCL-XL/BCL2L1) are frequently (over)expressed in B-NHL, which plays a crucial role in lymphoma pathogenesis, disease progression, and drug resistance." (PMID 32290241, 2020). "BCL2 expression is mostly absent in ALCL, ALK+ lymphomas but MCL1 expression can be detected in the majority of these lymphomas." (PMID 30131584, 2019). "MCL-1 has sequence similarity with BCL-2 and involved innormal development in lymphoma." (PMID 31285648, 2019). "Interestingly, in lymphomas from CD4-NPM-ALKLCKΔΔTyk2 mice, MCL1 expression was decreased at both the mRNA and protein levels as compared to CD4-NPM-ALK mice expressing TYK2 (P < 0.0001)." (PMID 30131584, 2019). "We noticed that the effect of a Low PROT diet over Mcl-1 expression levels was very variable among experiments and not sufficient to sensitize lymphoma-bearing mice to ABT-737 treatment." (PMID 27689327, 2016). "The reduced MCL-1 protein expression appeared to be accompanied by a significant decrease in BIM protein expression in the Eμ-Myc;CD19-Cre;Mcl-1fl/+and Eμ-Myc;CD19-Cre;Mcl-1fl/fl lymphomas tested." (PMID 26962682, 2016). "Overall, our results indicate that lowering carbohydrates but not protein intake is sufficient to reduce Mcl-1 expression and to sensitize lymphomas in mice to treatment with ABT-737." (PMID 27689327, 2016). "The lymphoma-free survival of the control mice without Mcl-1 deletion (Eμ-Myc and Eμ-Myc;CD19-Cre) was similar: median survivals of 91 days and 117 days, respectively (Mantle–Cox Log-rank test P=0.069)." (PMID 26962682, 2016). "In all tested lymphoma lines, drug treatment led to increases of the proapoptotic proteins (Bim, Bad, and PUMA) and downregulation of the antiapoptotic proteins (BCL-XL and MCL-1)." (PMID 26557706, 2015). "Additionally, sorafenib might downregulate Mcl-1, which is implicated in resistance to anticancer drugs and is overexpressed in a significant proportion of diffuse large B cell lymphoma (DLBCL) and follicular lymphoma (FL), thereby restoring lymphoma cell sensitivity to apoptosis." (PMID 23620775, 2013).